ARHGAP4 (Rho GTPase activating protein 4)
Description:
Inhibitory effect on stress fiber organization. May down-regulate Rho-like GTPase in hematopoietic cells.
Synonyms: KIAA0131; RGC1; RHOGAP4; C1; p115; SrGAP4
Tractability: PROTAC: ubiquitination databases record sites on it; its protein half-life has been measured.
Gene: Protein-coding gene on chromosome X (153,907,367 to 153,934,999, reverse strand). Ensembl gene ENSG00000089820.
Subcellular location: Cytoplasm
Subcellular location (Human Protein Atlas): Cytosol
Pathways (Reactome):
Signal Transduction: CDC42 GTPase cycle; RAC1 GTPase cycle; RHOA GTPase cycle
Gene Ontology:
Molecular function: protein binding; GTPase activator activity
Biological process: cytoskeleton organization; negative regulation of cell migration; nervous system development; regulation of small GTPase mediated signal transduction; regulation of synapse assembly; Rho protein signal transduction; negative regulation of axon extension; negative regulation of fibroblast migration; signal transduction
Cellular component: cytoplasm; cytosol; growth cone; microtubule
Homologues: Orthologues: chimpanzee ARHGAP4 (99% identical), macaque ARHGAP4 (97% identical), dog ARHGAP4 (87% identical), rat Arhgap4 (83% identical), rabbit ARHGAP4 (82% identical), mouse Arhgap4 (81% identical), pig ARHGAP4 (80% identical), tropical clawed frog arhgap4 (49% identical), zebrafish arhgap4b (45% identical), zebrafish arhgap4a (38% identical), Caenorhabditis elegans srgp-1 (28% identical). Paralogues in human: SRGAP3 (46% identical), SRGAP1 (45% identical), SRGAP2 (42% identical), SRGAP2B (22% identical), SRGAP2C (21% identical).
Diseases named in the same sentence as ARHGAP4 in open-access papers:
ARHGAP4 is named in the same sentence as 30 diseases in open-access papers, as found by Europe PMC text mining. Sharing a sentence is not in itself a finding about the gene and the disease. The quoted sentences say what the papers report.
pancreatic cancer (6 papers, 2020 to 2025). "ARHGAP4 has been reported to play an important role in regulating cell migration and invasion in pancreatic cancer." (PMID 34804963, 2021). "Decreased Rho GTPase-activating protein 4 (ARHGAP4) facilitates aerobic glycolysis of pancreatic cancer through activating HIF-1α pathway and upregulating M2 isoform of pyruvate kinase (PKM2) expression." (PMID 32587480, 2020). "Furthermore, in pancreatic cancer, miRNA-939-5p has been demonstrated to promote tumour migration and invasion by targeting ARHGAP4." (PMID 40016789, 2025). "ARHGAP4 regulates HDAC2 degradation by ubiquitination and enhances the expression of the Wnt/β-catenin signal pathway by regulating β-catenin activation, thus promoting the invasion and metastasis of pancreatic cancer." (PMID 38087046, 2024).
breast carcinoma (3 papers, 2019 to 2024). "FGD3 is implicated in breast cancer and ARHGAP4 in ovarian tumors." (PMID 30704450, 2019). "Studies have reported that SEPT9 promotes breast cancer EMT through activation of the FAK/Src signaling pathway by negatively regulating the ARHGAP4 protein in the Rho-GAP family." (PMID 39466813, 2024). "As an example, ARHGAP4, a member of the Rho family of GTPases, is involved in the regulation of the cell morphology of breast cancer-derived cells." (PMID 35409322, 2022).
colorectal cancer (3 papers, 2022 to 2024). A primary or metastatic malignant neoplasm that affects the colon or rectum. "The aim of this study is to explore the mechanism by which ARHGAP4 regulates the proliferation and growth of colon cancer cells, and it relates to the metastasis of colorectal cancer (CRC)." (PMID 38938545, 2024). "Moreover, the high expression of ARHGAP4 in colorectal cancer is related to the immune cells such as B cells, CD8+ and CD4+ T cells, macrophages, neutrophils, and dendritic cells." (PMID 38355537, 2024). "This study aims to analyze the correlation between ARHGAP4 in the expression and clinical characteristics of colorectal cancer (CRC), and the influence of ARHGAP4 expression on the prognosis of CRC, and to evaluate whether ARHGAP4 is a potential prognostic oncotarget for CRC." (PMID 35847897, 2022).
colon cancer (2 papers, 2022 to 2024). "We plan to further study the effect of ARHGAP4 on colon cancer cell proliferation and migration, as well as the molecular mechanism through cell and animal experiments." (PMID 35847897, 2022). "In colon cancer, the levels of B cells, macrophages, neutrophils, and dendritic cells are downregulated after the ARHGAP4 gene knockout." (PMID 35847897, 2022). "ARHGAP4 regulates the proliferation and growth of colon cancer cells by up- and downregulated cell cycle and differentiation-related molecules, which may be related to the metastasis of CRC." (PMID 38938545, 2024). "The expression of ARHGAP4 was highly correlated with the infiltration of CD4+ T cells in CRC and with dendritic cells in READ.In colon cancer, after ARHGAP4 gene knockout, the levels of B cells, macrophages, neutrophils, and dendritic cells are downregulated." (PMID 35847897, 2022). "In colon cancer, the B-cell, macrophage, neutrophil, and dendritic-cell levels are downregulated after ARHGAP4 gene knockout; the levels of CD8+ and CD4+ T cells, neutrophils, and dendritic cells are upregulated after the amplification of the ARHGAP4 gene." (PMID 35847897, 2022).
gastric cancer (2 papers, 2021 to 2024). A primary or metastatic malignant neoplasm involving the stomach. "In another study, ARHGAP4 was identified as a potential oncogene in gastric cancer, and its high expression was significantly associated with poor prognosis." (PMID 39268080, 2024).
bipolar disorder (1 paper, 2011). A disorder of the brain that causes unusual shifts in mood, energy, activity levels and the ability to carry out day-to-day tasks. "These genes included SBNO2, CEACAM5, AKAP1, UBC, ACTB, UBB, and FOS for schizophrenia; SEC24C, PGLYRP1, ARHGAP4, RPL22, SLC6A11, and SYK for bipolar disorder; and SRRT, PARK2, LILRA4, STK17A, IGFBP2, and NF1 for major depression." (PMID 22373040, 2011).
colon adenocarcinoma (1 paper, 2022). "The high expression of ARHGAP4 in select colon adenocarcinoma indicates a poor prognosis by database analysis." (PMID 35847897, 2022).
colorectal adenocarcinoma (1 paper, 2022). The most common type of colorectal carcinoma. "Immunohistochemistry (IHC) results showed that the IHC score of ARHGAP4 in colorectal adenocarcinoma was significantly higher than the score of adjacent normal tissues by pathologists observed." (PMID 35847897, 2022). "In colorectal adenocarcinoma, the ARHGAP4 high-expression group has poor prognosis." (PMID 35847897, 2022). "ARHGAP4 is negative or lower expression in normal tissues adjacent to cancer and high expressed in colorectal adenocarcinoma tissues." (PMID 35847897, 2022).
developmental delay (1 paper, 2021). "This case shows potential overlap of clinical presentation due to multiple deleterious variants, of which the LMX1A variant is the strongest etiology of inner ear abnormalities in this patient while the ZFHX4 or ARHGAP4 variants may explain ID3’s developmental delay." (PMID 33924653, 2021).
epilepsy (1 paper, 2021). A brain disorder characterized by episodes of abnormally increased neuronal discharge resulting in transient episodes of sensory or motor neurological dysfunction, or psychic dysfunction. "Overall, our data supports a model in which upregulation of circ_Arhgap4 may reduce the availability of miR-6328 leading to an increase of D2R, which may trigger protection against epilepsy-associated changes." (PMID 33584828, 2021).
female infertility (1 paper, 2024). Diminished or absent ability of a female to achieve conception. "Taken together, our study provided key evidences that management of female infertility with Cai’s Prescription was beneficial for poor ovarian responders, leading to increase of the number of high quality embryos, and ARHGAP4 may be a candidate target for POR treatment." (PMID 38355537, 2024).
gallbladder cancer (1 paper, 2024). "For these genes, some researchers have found that ARRB1 can promote the activation of the TAK1/MAPK pathway to promote the progression of gallbladder cancer, and ARHGAP4 can be targeted by miR-939-5p, thereby promoting the invasion and metastasis of pancreatic cancer." (PMID 38688945, 2024).
Immunodeficiency (1 paper, 2008). Failure of the immune system to protect the body adequately from infection, due to the absence or insufficiency of some component process or substance. "Taken together with the results of previous studies, our present results suggest that ARHGAP4 plays some role in lymphocyte differentiation, but does not cause the immunodeficiency phenotype." (PMID 18489790, 2008). "ARHGAP4 may play some role in lymphocyte differentiation but partial loss of ARHGAP4 does not result in clinical immunodeficiency." (PMID 18489790, 2008). "ARHGAP4 may play some role in lymphocyte differentiation but partial loss of ARHGAP4 dose not result in clinical immunodeficiency." (PMID 18489790, 2008). "Recently, an NDI patient lacking AVPR2 and all of ARHGAP4 showed immunodeficiency characterised by a marked reduction in the number of circulating CD3+ cells and almost complete absence of CD8+ cells." (PMID 18489790, 2008). "The patients in the present study lack the C-terminus of ARHGAP4 (amino acids 515–965 according to the reference sequence NM_001666), but none of them showed clinical signs of immunodeficiencies or neurologic disorders." (PMID 18489790, 2008). "In addition to the patients in the present study, five NDI patients with partial deletion of ARHGAP4 have been reported, and none showed clinical signs of immunodeficiency." (PMID 18489790, 2008). "ARHGAP4 is expressed at high levels in hematopoietic cells, and it has been reported that an NDI patient lacking AVPR2 and all of ARHGAP4 showed immunodeficiency characterised by a marked reduction in the number of circulating CD3+ cells and almost complete absence of CD8+ cells." (PMID 18489790, 2008).
viral infection (1 paper, 2016). "Furthermore, we confirmed by WB analysis the effect of viral infection with pLKO-shRNF10 on protein levels of some of the RNF10 target genes, such as Ophn1, ArhGap4 and ArhGef6." (PMID 26977767, 2016).
tumor (11 papers, 2021 to 2025). "Furthermore, in vitro assay also showed that the four risk genes (HSPA1A, SEMA4C, CDKN2A, ARHGAP4) were overexpressed in the tumor cells." (PMID 39950044, 2025). "Na Kang’s study reported that Septin9 is a negative regulator of ARHGAP4; ARHGAP4 promotes tumor migration and epithelial–mesenchymal transition by activating the focal adhesion kinase (FAK)/Src signaling pathway." (PMID 35847897, 2022). "Unfortunately, there have been few research advances on ARHGAP4 in the field of CRC and even in the entire field of tumor research." (PMID 39268080, 2024). "Other RhoGAPs, such as ARHGAP4, ARHGAP6, ARHGAP9, ARHGAP12 and ARHGAP25, have also demonstrated tumor suppressor roles in different types of tumors 26-30." (PMID 36168627, 2022). "The difference analysis of 41 paired samples of TCGA-COAD showed that the mRNA levels of ARHGAP4, SIAH2, TRIM45, and WDR72 were significantly upregulated in the tumor group, while MID2 and UBE2D2 showed no statistical difference." (PMID 39268080, 2024). "There is no research on the roles of ARHGAP4 and HAOPLN3 in PCa, but the existing evidence indicates that their functions in tumor recurrence and metastases should not be ignored." (PMID 34804963, 2021).
cancer (3 papers, 2017 to 2025). A tumor composed of atypical neoplastic, often pleomorphic cells that invade other tissues. "In our clinical data results, ARHGAP4 is highly expressed in CRC and lowly expressed in normal tissues adjacent to cancer." (PMID 35847897, 2022). "Similarly, our clinical data analysis results show that ARHGAP4 is highly expressed in CRC and lowly expressed in normal tissues adjacent to cancer." (PMID 35847897, 2022).
degenerative disease (1 paper, 2022). "As no specific or robust link between the ARHGAP4/CFAP47 genes and PHA has been identified to date, further research will be needed to understand whether they contribute to the incidence of this degenerative disease." (PMID 36401472, 2022).
ARHGAP4 also shares sentences with these, for which no sentence is quoted: nephrogenic diabetes insipidus (3 papers); infection (2); autoimmune disease (1); chronic hepatitis (1); glioblastoma (1); head and neck squamous cell carcinoma (1); Intellectual disability (1); major depression (1); neurologic disorders (1); Opportunistic infection (1); ovarian tumors (1); prostate carcinoma (1); schizophrenia (1).